SNORA14A (small nucleolar RNA, H/ACA box 14A)
Synonyms: ACA14a
Gene: Small nucleolar RNA gene on chromosome 7 (75,943,782 to 75,943,916, forward strand). Ensembl gene ENSG00000201643.
Gene Ontology:
Biological process: RNA processing
Cellular component: nucleolus
Homologues: Orthologues: macaque SNORA14A (96% identical), guinea pig SNORA14A (88% identical), mouse Gm26397 (85% identical), rat LOC120098679 (85% identical). Paralogues in human: SNORA14B (91% identical).